HK2 (hexokinase 2)
Diseases named in the same sentence as HK2 in open-access papers (continued):
Sharing a sentence is not in itself a finding about the gene and the disease.
hepatocellular carcinoma (continued). "It has been reported that ELAVL1 can suppress the expression of HK2 and pyruvate kinase-M2 (PKM2) by specifically binding to miR-199a precursor, consequently promoting the proliferation and growth of hepatocellular carcinoma." (PMID 39390359, 2024). "Many studies had confirmed that the increased expression of HK2 and LDHA promoted the glycolysis process of tumor cells, thus accelerating the malignant phenotype of tumors, such as hepatocellular carcinoma and bladder cancer." (PMID 38218855, 2024). "In hypoxic hepatoma cells and xenografted models, ginsenoside CK in a dose of 20–60 μM down-regulated the protein level of HIF1α, glycolysis, GLUT1, glycolytic enzymes HK2, and LDHA, as well as PDK1." (PMID 38001865, 2023). "Among the subtypes, HK2 is considered the most important one, which is overexpressed in various tumors including breast, lung, gastric and laryngeal squamous cancer, hepatocellular carcinoma (HCC), and renal cell carcinoma." (PMID 37190124, 2023). "Similarly, the LINC02432/hsa-miR-98–5p/HK2 axis also correlated with SIGLEC15 regulation in hepatocellular carcinomas (HCC)." (PMID 37869015, 2023). "In hepatoma and nonsmall cell lung cancer (NSCLC), upregulation of circPRMT5 facilitates cancer progression via targeting HK2 or EZH2." (PMID 36161608, 2022). "CK triggered apoptosis in human hepatocellular carcinoma HCCs, HepG2 and Huh7 cells via the AKT/mTOR/c-Myc/HK2/PKM2 pathway." (PMID 36339566, 2022). "The newly identified HK2‐acyl‐CoA synthetase long chain family member 4 (ACSL4)‐fatty acid β‐oxidation axis is an ideal therapeutic target for hepatocellular carcinoma (HCC), and GalNac‐conjugated siHK2 opens an avenue to develop a novel strategy of precision therapy for the treatment of HCC." (PMID 35603967, 2022). "In conclusion, Rg3 has a synergistic effect on the sensitivity of HepG2 and Bel7404 hepatoma cells to SFN, which is related to HK2-mediated glycolysis and the PI3K/Akt signaling pathway." (PMID 35719058, 2022). "Dauricine, an alkaloid, can effectively decrease the expression of HK2 and PKM2 by up-regulating miR-199a, making hepatocellular carcinoma cells more sensitive to chemotherapy treatment." (PMID 36339566, 2022). "During the cancerous transformation of normal hepatocytes into hepatocellular carcinoma (HCC), the enzyme catalyzing the first rate-limiting step of glycolysis, namely the glucokinase (GCK), is replaced by the higher affinity isoenzyme, hexokinase 2 (HK2)." (PMID 33594203, 2021). "In hepatocellular carcinoma, the expression of HIF-1α and its target genes LDHA and hexokinase 2 (HK2) is inhibited by balanophorin B under hypoxia, resulting in the suppression of glycolysis in vitro." (PMID 34575983, 2021). "A study revealed that the co-administration of DOX and apigenin dwindled the expression of hexokinase 2 (HK2) and lactate dehydrogenase A (LDHA) in the human hepatocellular carcinoma cell line, HepG2." (PMID 34715860, 2021). "Further evidence showed that miR-125b targets hexokinase 2 (HK2), which supports cell survival and the tumorigenesis of hepatocellular carcinoma." (PMID 33066509, 2020). "For further investigation, we used 3‐BP, inhibiting HK2 bound to VDAC1, and observed that CTB contributed to the opening of mPTP and the destruction of MMP in hepatoma cells." (PMID 31994339, 2020). "Our extensive analysis revealed that the activities of hepatoma cells, including proliferation, invasion, migration, apoptosis, glycolysis, and autophagy, were significantly affected by USP14 through its interaction with HK2." (PMID 38383348, 2024). "In hepatocellular carcinoma, UBR7 inhibits glycolysis by indirectly suppressing HK2 expression." (PMID 38495480, 2024). "In models of hepatitis B virus–related hepatocellular carcinoma and in sarcoma cell lines, classical NFKB signaling (RELA) controls metabolic substrate preference in favor of glycolysis through transcriptional upregulation of HK2." (PMID 38272231, 2024).
hepatocellular carcinoma (continued). "Furthermore, we observed that the overexpression of HK2 partially attenuated the inhibitory effect of USP14 on the AKT and P62 signaling pathways in hepatoma cells." (PMID 38383348, 2024). "In addition to HK2 and LDHA, some researchers discovered that NR3C2 inhibits cellular aerobic glycolysis by regulating PKLR, an isozyme of pyruvate kinase, in hepatocellular carcinoma cells." (PMID 36950803, 2023). "The combined exposure of HK2 (3-bromopyruvate) and PDI inhibitors (bacitracin) resulted in the reduction of microvessel densities, (a surrogate marker for tumor angiogenesis), in an in vivo model of hepatocellular carcinoma." (PMID 36984785, 2023). "Indeed, resveratrol suppressed EGFR, Akt, and ERK1/2 activation, which led to inhibition of HK2-mediating glycolysis in NSCLC; down-regulated HK2 in hepatocellular carcinoma both in vitro and in vivo." (PMID 38001865, 2023). "Also, hexokinase 2 (HK2), rate-limiting enzyme of the glycolytic pathway, is selectively damaged by autophagy in liver carcinoma." (PMID 36160153, 2022). "Similarly, a 2020 study showed that CAFs transfer circRNA via EVs to hepatocellular carcinoma (HCC), thereby enhancing glycolysis through regulating HK2 expression." (PMID 35563739, 2022). "Knocking out of the YAP gene in human hepatocellular carcinoma (HCC) cell lines, HepG2, and MHCC97L cells, cultured in the stiff ECM, resulted in downregulation of glycolytic enzymes HK2 and LDHA, which subsequently reduced the migration capacity of cancer cells." (PMID 33718214, 2021). "The 3-BrPA-induced -severe- reduction of GAPDH, but not HK2, cellular contents in T24 (and T24-X) can be associated with drug’s potency to strongly inhibit GAPDH, but not HK2, glycolytic activity in hepatocellular carcinoma cells." (PMID 26198749, 2015). "Hexokinase 2 (HK2)-mediated glycolysis was also shown to be inhibited following quercetin treatment (25~50 μM) in Bel-7402 and SMMC-7721 hepatocellular carcinoma (HCC) cells." (PMID 36611972, 2023). "In multiple types of cancer including hepatocellular carcinoma (HCC), galectin-3 is highly expressed, and its level of expression is positively correlated with that of HK2 and PKM2 and negatively correlated with the prognosis of HCC patients." (PMID 36481721, 2022). "In hepatocellular carcinoma (HCC), METTL3 expression positively correlated with glycolysis genes SLC2A1, HK2, PFKM and PKM." (PMID 33669361, 2021). "Furthermore, mRNA expression of hexokinase 2 (HK II), which catalyzes the phosphorylation of glucose to glucose-6-P, corelates with HIF-1α protein in hepatocellular carcinoma cells and metastatic liver cancer, and HK II and HIF-1α protein expression co-localized in these cancer cells." (PMID 34360716, 2021). "Therefore, MJ may function by affecting the combination of HK2 and VDAC1 which occurs in other types of hepatoma cells." (PMID 28498814, 2017). "Dauricine (Dau), another alkaloid, was found to efficiently decrease HK2 and PKM2 gene expression in hepatocellular carcinoma HCC cells by increasing the expression of miR-199a, hence increasing the chemosensitivity of HCC cells to some chemotherapy medicines like cisplatin and sorafenib." (PMID 36339566, 2022). "MJ has been shown to cleave HK1 and HK2 from VDAC in a dose-dependent manner in the mitochondrial fraction of CT-36 mouse colon carcinoma cells, MOLT-4 human leukemia, BCL1 mouse leukemia, B16 mouse melanoma and HCC hepatocellular carcinoma (LM3, BEL-7402, Hep3B, SMMC-7721)." (PMID 34068337, 2021).
lung cancer (112 papers, 2013 to 2025). A malignant neoplasm involving the lung. "HK2 expression is also elevated in lung cancer, and shows significant association with the tumor stage." (PMID 36768924, 2023). "A recent study has revealed that HK2 identifies a novel circulating tumor cell population associated with poor prognosis in lung cancer patients." (PMID 36335239, 2022). "HK2 plays a critical role in KRAS-dependent tumorigenesis in mouse lung cancer models, and in other cancers, with loss of HK2 attenuating tumor phenotypes and improving survival." (PMID 35410460, 2022). "The oncogenic K-Ras was associated with higher levels of hexokinase 2 (HK2), involved in high-rate metabolism of the glucose in lung cancer-associated TCA according to higher consumption of glutamine." (PMID 33187551, 2020). "Our work presents evidence that alteration of HIF1 in lung cancer cells is associated with HK2 and GBE1." (PMID 28423489, 2017). "Importantly, HK2 was demonstrated as a metabolic function-associated biomarker for detecting circulating tumour cells in the peripheral blood of lung cancer patients that showed dismal outcome and poor response to therapy." (PMID 36765947, 2023). "Besides, hexokinase 2 (HK2) is an essential enzyme associated with glucose metabolism and is necessary for glycolysis, proliferation, and migration in lung cancer." (PMID 35379058, 2022). "In general, our results confirmed that the AKT-GSK3β-c-Myc-HK2 was the critical pathway regulated by the dose-dependent Daurisoline in lung cancer cells, and we proved Daurisoline was the potential therapeutic oncology drug." (PMID 39699276, 2025). "In this study, we demonstrate that Daurisoline targets glycolysis and reduces the protein level of HK2, thereby inhibiting lung cancer progression." (PMID 39699276, 2025). "Integrated genomics and metabolomics in lung cancer revealed BCKDK as an upstream regulator of MYC-dependent HK2 transcription, supporting dual BCKDK/HK2 inhibition to counter trametinib resistance." (PMID 40693266, 2025). "The deletion of the Hk2 gene in lung cancer cells ameliorated glucose-derived ribonucleotides and glutamine-derived carbon utilization in anaplerosis." (PMID 36768924, 2023). "Recent findings have revealed that circPUM1 upregulated the expression levels of glucose transporter 1(GLUT1) and hexokinase-2 (HK2) to promote the glycolysis of lung cancer by upregulating METTL3." (PMID 35331234, 2022). "In lung cancer, miR-143 reduces the expression of hexokinase 2 (HK2) protein by targeting the mammalian target of rapamycin (mTOR) pathway." (PMID 35093153, 2022). "Molecular pathway study shows that exosomal circ-0008928 enhances HK2 expression in triggering glycolysis and mediating drug resistance in lung cancer." (PMID 35765040, 2022). "BACH1 promotes lung cancer cell migration and invasion by inducing the expression of metabolic genes (such as HK2) leading to an increase in glycolysis, and thus BACH1 inhibitors have the potential to reduce the spread of lung cancer cells." (PMID 35313207, 2022). "LncRNA-IGFBP4-1 has been demonstrated to increase ATP production in lung cancer cells by upregulating metabolism enzymes expression, including HK2, LDHA, and PDK1." (PMID 36072431, 2022). "Apart from these studies, the role of miR-143 in modulating HK2 has been reported in various cancers like colon cancer, esophageal squamous cell carcinoma, lung cancer, cervical carcinoma, liposarcoma, bladder cancer, osteosarcoma, and gastric cancer." (PMID 36013278, 2022).
lung cancer (continued). "Keap1 loss and Nrf2 activation promotes lung cancer metastasis by accumulating BTB domain and CNC homolog 1 (Bach1), which has been reported to stimulate transcription of HK2 triggering glycolysis-induced metastasis." (PMID 36419136, 2022). "Selective inhibitors for glycolytic enzymes, such as HK2, have been developed and are currently used in the treatment of lung cancer 34 and prostate cancer." (PMID 33994862, 2021). "Our previous work suggested that another LSD1 inhibitor ORY-1001 inhibits lung cancer cell growth and induces cell apoptosis by triggering HK2-mediated cellular events." (PMID 34235156, 2021). "Kaplan–Meier plots demonstrate that the high levels of HK2, SLC2A1 (GLUT1), LDHA, and HIF1a expression were associated with poor survival of lung cancer patients." (PMID 34692483, 2021). "Studies have been done on the cancer cell lines and mice models to indicate that HK2 is exclusively upregulated in lung cancer." (PMID 33916349, 2021). "We then found that Oct4 and HK2 are upregulated in lung CSCs or lung cancer cells with collagen XVII overexpression." (PMID 31928533, 2020). "Deletion of hexokinase 2 (Hk2) in lung cancer cells suppressed glucose derived ribonucleotides and impaired glutamine derived carbon utilization in anaplerosis." (PMID 32560574, 2020). "HK2 has already been shown to be upregulated upon HGF stimulation in a lung cancer model and to promote the proliferation and survival of laryngeal squamous cell carcinoma." (PMID 31940827, 2020). "More importantly, expression of collagen XVII, Oct4, and HK2 predicts a poorer prognosis in patients with lung cancer." (PMID 31928533, 2020). "Using commercial kits, we found that circHIPK3 knockdown reduced the glucose consumption, lactate production, and the enzyme activity of HK2, suggesting that circHIPK3 knockdown weakened glycolysis in lung cancer H1975 and A549 cells." (PMID 33817257, 2020). "We used immunohistochemistry to investigate the clinical significance of collagen XVII, Oct4, and HK2 expression in tumor specimens from a cohort of 79 patients who received lung resection for lung cancer." (PMID 31928533, 2020). "Degradation of miR-216a-5p targets is the dominant effect of miR-216a-5p in cancer, including (i) inhibition of hexokinase-2 in uveal melanoma and (ii) down-regulation of matrix metalloproteinase 16 in lung cancer." (PMID 31297133, 2019). "Lung cancer initiation and progression are significantly inhibited in Hk2-knockout mice, whereas the upregulation of HK2 can induce EMT due to metabolic reprogramming." (PMID 31027222, 2019). "Overexpression of HK2 predicts poor patient survival rate in colon cancer, lung cancer, and glioblastoma 20-23." (PMID 31595166, 2019). "Cancer cells highly upregulate HK2 compared to their normal tissue of origin and it is required for tumorigenesis in a variety of mouse cancer models, including breast and lung cancer and T cell leukemia." (PMID 30140438, 2018). "Together, these results suggest that ORY-1001 affects lung cancer cell proliferation and apoptosis through regulating HK2 expression." (PMID 30568590, 2018). "Firstly, ORY-1001 treatment resulted in decreased cell proliferation of lung cancer cells, including H1299 and A549 cells, in a time and dose-dependent manner, but this effect was rescued in H1299 and A549 cells, when HK2 was over expressed." (PMID 30568590, 2018). "At the same time, the decreased cell cycle of lung cancer cells was also rescued by the overexpression of HK2." (PMID 30568590, 2018). "Although HK1+HK2+ lung cancer H460 cells are resistant to this therapeutic combination, isogenic HK1KOHK2+ cells are sensitive to this therapy." (PMID 29988332, 2018). "Previously, we showed that systemic deletion of HK2 in mice is well tolerated and is therapeutic for lung cancer." (PMID 29687779, 2018). "Evidence from previous studies suggests that HK2 depression inhibits human and mouse lung cancer cell growth by inducing cell apoptosis." (PMID 28881757, 2017).
lung cancer (continued). "We also observed that GBE1 and HK2 are downstream of HIF1 pathway important in hypoxia-conditioned lung cancer cell." (PMID 28423489, 2017). "The result from laboratory transgenic mice model study has demonstrated that HK2 is required for tumor initiation and maintenance in KRas-driven lung cancer." (PMID 28427230, 2017). "Emerging documents have demonstrated that increased HK2 expression leads to promotion of cell proliferation and inhibition of apoptosis in many cancers including ovarian, breast and lung cancer." (PMID 29043013, 2017). "In lung cancer cell lines, HK2 was required for the human and mouse lung cancer cell growth; inhibition of HK2 inhibited human and mouse lung cancer cell growth through inducing cell apoptosis and autophagy." (PMID 28423489, 2017). "Genetic deletion of HK2 in a preclinical model of Kras driven lung cancer was sufficient to alter glucose metabolism and improve overall survival, suggesting that direct targeting of HK2 would be beneficial in PDAC." (PMID 28915575, 2017). "The convergence of HIF1 and HK2/GBE1 in the lung cancer patients with OSAS raises important questions regarding the underlying mechanism of OSAS-lung cancers." (PMID 28423489, 2017). "Genetic deletion of HK2 has been reported to reduce the overall tumor burden in lungs in a genetic mouse lung cancer model, indicating a role of HK2 in tumor initiation." (PMID 29137232, 2017). "As expected, up-regulation of HK2 in the four independent Kras-knockdown lung cancer cells rescued the phenotypes that cell growth was inhibited in Kras-knockdown cell lines in vitro." (PMID 26884725, 2016). "Taken together, these studies showed that the 2-DG, HK2 inhibitor, suppresses lung cancer cell growth in vivo." (PMID 26884725, 2016). "Hk2 has been identified as an attractive target for KRAS-driven lung cancers as whole-body deletion of Hk2 in the mouse selectively targets tumor cells." (PMID 27096871, 2016). "Our pharmacological studies confirmed that 2-DG, an inhibitor of HK2, inhibited human and mouse lung cancer cell growth through inducing cell apoptosis and autophagy." (PMID 26884725, 2016). "Genetic studies revealed that HK2 was required for the human and mouse lung cancer cell growth in vitro and in vivo." (PMID 26884725, 2016). "In NSCLC cells, HK2 was found to promote glycolysis and chemoresistance of lung cancer cells." (PMID 38082439, 2023). "However, lncRNA HOTAIR can collaborate with FTO to remove the methylation modification of HK2 mRNA, thereby increasing the expression of HK2 and promoting glycolysis and proliferation of lung cancer." (PMID 37582735, 2023). "Furthermore, HK2+/CK−‐circulating tumour cells exhibited poor responses to treatment and were related to unfavourable clinical outcomes in patients with lung cancer." (PMID 37846760, 2023). "Previous study showed that lung cancer cell HK2 overexpression suppressed T-cell effector functions, and that the increased HK2 expression was inversely correlated with the expression of T-cell effector molecules according to analysis of The Cancer Genome Atlas in lung cancer." (PMID 36320008, 2022). "miR-214 promotes lung cancer cell proliferation and glycolysis by targeting HK2 and PKM2." (PMID 34336555, 2021).